H19 (H19 imprinted maternally expressed transcript)
Diseases named in the same sentence as H19 in open-access papers (continued):
Sharing a sentence is not in itself a finding about the gene and the disease.
cancer (continued). "The long non‐coding H19 correlates with higher risk of cancer death in multiple cancers, and Heatmap result of TCGA data base revealed the co‐overexpression of both H19 and Wnt factors." (PMID 30338598, 2019). "Nevertheless, these results provide no consensus regarding the promotive or protective effect of individual H19 SNPs on cancer risk." (PMID 31277475, 2019). "Some original studies and previous meta-analyses reported the relationship between H19 rs217727 and cancer risk, but the results were inconsistent." (PMID 31752724, 2019). "H19 gene has been reported as a cancer-associated lncRNA that functions as both oncogene and suppressor gene." (PMID 31772668, 2019). "Elevated expression of lncRNA H19 (H19) in the setting of hypoxia has been implicated as a promising therapeutic target for various cancers." (PMID 31170091, 2019). "Several studies have been performed to explore diagnostic value of lncRNA H19 in cancer detection and diagnosis." (PMID 31016202, 2019). "We have performed this study to evaluate the association between H19 rs217727 polymorphism and the risk of cancer." (PMID 31752724, 2019). "All of the results revealed that lncRNA H19 had a relatively moderate diagnostic accuracy in cancer detection and diagnosis." (PMID 31016202, 2019). "Growing evidence showed that this H19 gene-encoded 2.3 kb lncRNA functioned in tumorigenesis and cancer progression." (PMID 31299871, 2019). "Several studies have been done to explore diagnostic value of lncRNA H19 in cancer detection and diagnosis." (PMID 31016202, 2019). "Exosomes derived from carcinoma-associated fibroblasts transfer lncRNA H19 into CRC cells to enhance oxaliplatin-resistance." (PMID 31712601, 2019). "As H19 play a crucial role in embryogenesis and controls the expression of two major pluripotency factors—Oct4 and Sox2, it promotes cancer stemness, which is associated with poor prognosis in cancer patients." (PMID 30154386, 2018). "Abnormal expression or loss of imprinting of H19 has also been linked to diverse human cancers including hematological malignancies." (PMID 29643943, 2018). "It is well accepted that lncRNA-H19 works importantly in the incidence and prognosis of cancers and SNPs in H19 can be used as a promising biomarker for cancers risk." (PMID 29511035, 2018). "H19 is a maternally expressed imprinted gene on chromosome 11p15.5 that encodes for a capped and spliced RNA and has been implicated in cancer." (PMID 30071841, 2018). "In recent studies, most of meta-analyses were conducted to focus on the association between lncRNA HOTAIR or lncRNA ZNRD1-AS1 or lncRNA POLR2E or lncRNA H19 polymorphisms and cancer risk." (PMID 29802154, 2018). "Recent meta-analyses showed that the genetic variants of H19 (e.g., allele rs2839698) exhibited a significantly higher risk of developing cancer." (PMID 30154386, 2018). "The expression of lncRNA H19 and miR-675 were associated with repression of extracellular matrix protein, TGFβ1, that regulate cellular migration and cancer metastasis." (PMID 29579063, 2018). "Up to the present, some studies have shown the relationship between H19 polymorphisms and several types of cancer." (PMID 30219045, 2018). "Due to the relationship between H19 variants and cancer risk as well as prognosis is still needed to be clarified; the H19 polymorphisms have been of great interest in the recent years." (PMID 29511035, 2018). "Odds ratios (ORs) and corresponding 95% confidence interval (CIs) from these studies were used to detect associations between H19 polymorphisms and cancer risk using five genetic models." (PMID 28404885, 2017). "The association between the H19 rs2839698 G>A polymorphism and cancer risk was examined in five relevant studies involving 3,369 patients and 3,510 healthy controls." (PMID 28404885, 2017). "In cancer, H19 is frequently overexpressed and it is associated to many aspect of cancer development." (PMID 29099749, 2017).
cancer (continued). "We conducted this meta-analysis of eleven studies to more accurately assess the associations between the lncRNA H19 polymorphisms rs2839698 G>A, rs217727 G>A and rs2107425 C>T polymorphisms and cancer risk." (PMID 28404885, 2017). "Previous epidemiological research suggests polymorphisms in long non-coding RNA (lncRNA) H19 are associated with an increased risk of cancer, but the results are inconsistent." (PMID 28404885, 2017). "Many genes involved in embryonic growth and implicated in cancer lie within the H19 locus and are cis regulated by H19." (PMID 29113413, 2017). "The association between lncRNA H19 rs217727 G>A polymorphism and cancer risk was examined in five studies involving 3,334 cases and 3,768 controls." (PMID 28404885, 2017). "In contrast, the T allele variant of the lncRNA H19 rs2107425 C>T polymorphism had a protective effect against cancer development, especially in Caucasian population." (PMID 28404885, 2017). "The association between the H19 rs2107425 C>T polymorphism and cancer risk was examined in eight studies involving 10,856 patients and 15,612 healthy controls." (PMID 28404885, 2017). "Associations have also been reported between the three most common SNPs in H19 (rs2839698 G>A, and rs217727 G>A, rs2107425 C>T) and cancer susceptibility." (PMID 28404885, 2017). "We therefore conducted a meta-analysis to more accurately determine the association between lncRNA H19 polymorphisms and cancer risk." (PMID 28404885, 2017). "The up-regulation of several other lncRNAs, such as HOTAIR and MVIH, and the downregulation of H19 have been associated with poor prognosis in cancers." (PMID 28346506, 2017). "Loss of expression of H19 served as a positive control in these experiments and was consistent with it being frequently the target of loss-of-imprinting events in human cancers." (PMID 28587163, 2017). "For H19, several studies investigated the association between SNPs and cancer risk, among which there were four studies about rs2107425." (PMID 28159929, 2017). "Although only eleven studies involving relatively small sample sizes of 14,030 cases and 19,179 controls were included, these results help to characterize associations between lncRNA H19 polymorphisms and cancer risk." (PMID 28404885, 2017). "We performed a meta-analysis to summarize the results of common lncRNAs (HOTAIR, PRNCR1, POLR2E and H19) polymorphisms on cancer risk, by using the random-effect model to obtain the odds ratio (ORs) and 95% confidence interval (95%CI)." (PMID 28159929, 2017). "H19 is located at chromosome 11p15.5 encoding a 2.3 kb lncRNA, is frequently deregulated in tumors, and contributes to both cancer initiation and progression." (PMID 27926484, 2017). "For example, loss of imprinting at the H19 locus resulted in high H19 expression in cancers of the esophagus, colon, liver, bladder and with hepatic metastases." (PMID 27351280, 2016). "Increasing evidence suggests that H19 genetic variants play important roles in cancer development as well as other diseases." (PMID 27765929, 2016). "The strength of our meta-analysis stems from systematically reviewing the relationships between three H19 polymorphisms (rs2107425, rs2839698 and rs217727) and cancer susceptibility for the first time." (PMID 27732938, 2016). "Growing evidences showed that this H19 gene-encoded 2.3 kb lncRNA functioned in tumorigenesis and cancer progression." (PMID 27825121, 2016). "As expected, the association of two SNPs (rs2839698 and rs217727) together with rs2107425 in H19 with cancers susceptibility has attracted much interest in subsequent research." (PMID 27732938, 2016). "Among the studies that explored the relationships between H19 SNPs with cancer risk, one focused on 3 SNPs (rs2107425, rs2839698 and rs217727), and four focused on 2 SNPs, while the other five focused on only one SNP." (PMID 27732938, 2016).
cancer (continued). "As expected, the associations of H19 polymorphisms with cancer sensitivities have attracted much interest, with particular focus on H19 rs2839698 and rs217727." (PMID 27732938, 2016). "Reports on the relationship between the lncRNA H19 rs217727 polymorphism and the risk of cancer in the Chinese population have been inconsistent." (PMID 27486980, 2016). "Among lncRNAs, we confirm previously-reported downregulation of GAS5 and MEG-3, and identify for the first time dysregulation of cancer-associated H19 and PCAT-1 in HNSCCs." (PMID 27323410, 2016). "Although there have been several recent studies that examined possible links between polymorphisms in H19 and cancer risk, the results have been inconclusive." (PMID 27732938, 2016). "The long noncoding RNA H19 has been implicated in development and growth control and is associated with human genetic disorders and cancer." (PMID 26376677, 2015). "Recently, the long non-coding RNA (lncRNA) H19 has been identified as an oncogenic gene in multiple cancer types and elevated expression of H19 was tightly linked to tumorigenesis and cancer progression." (PMID 26068968, 2015). "The correlation between this risk, which indeed exists for several cancers and H19 levels in the RA synovial tissue is yet to be tested." (PMID 23429271, 2013). "A key feature of cancer is the loss of this imprinting, which results in the well documented overexpression of H19 in cancers of the colon, liver, breast and bladder and in hepatic metastases, compared to healthy tissues." (PMID 23887658, 2013). "We have previously shown that loss of IGF2 imprinting in cancer is accompanied by loss of normal long-range intrachromosomal interactions involving the IGF2/H19 locus." (PMID 24019942, 2013). "While these reactivated fetal lncRNAs represented mostly uncharacterized examples, H19, a well-studied lncRNA with associations in both mammalian development and cancer, was also detected in our dataset." (PMID 21991387, 2011). "Additionally, lncRNAs represent potential biomarkers or therapeutic targets to enhance existing treatments; for example, the exosomal lncRNA H19—which is secreted by cancer-associated fibroblasts—has been associated with chemoresistance." (PMID 40429961, 2025). "In addition, H19 has been implicated in the inhibition of apoptosis, enabling cancer cells to survive despite chemotherapy-induced DNA damage." (PMID 40142329, 2025). "Blocking cancer‐causing RNAs such as MALAT1 or H19 may interfere with the ways that tumors stay alive through autophagy and make cancer cells more sensitive to traditional chemotherapies." (PMID 40671967, 2025). "The findings of this study highlight the diagnostic potential of H19 in cancer and suggest that it may serve as a promising prognostic marker for solid tumors." (PMID 38166752, 2024). "Moreover, the high expression of H19 shortened the survival time of cancer patients and was closely associated with poor prognosis of cancer patients." (PMID 39309008, 2024). "This expression correlates with cancer progression, metastasis, and poor prognosis, suggesting that H19 may be used as a diagnostic and prognostic biomarker." (PMID 39659621, 2024). "In addition, abnormal H19 overexpression is thought to be associated with cancer development and progression, making it a potential prognostic indicator and therapeutic target for treating specific cancers." (PMID 38355574, 2024). "Given the association of H19 with the development of various cancers, these variants are potentially crucial for studying disease mechanisms and clinical diagnostics, warranting further investigation into their precise functional roles and their impact on disease progression." (PMID 39267845, 2024). "Our results supported that H19 SNPs were significantly correlated with cancer risk." (PMID 37480014, 2023).
cancer (continued). "Similarly, studies demonstrated the strong association between EZH2 and H19 to suppress Wnt antagonist genes to activate Wnt/β-catenin signaling in cancer development." (PMID 36960964, 2023). "Similarly, with a prior probability of 0.25, the homozygote model of H19 rs3024270 polymorphism was associated with cancer risk and the recessive model of H19 rs3024270 polymorphis was associated with cancer risk (P < 0.2)." (PMID 37480014, 2023). "H19 rs2839698 and rs3024270 were closely associated with overall cancer risk." (PMID 37480014, 2023). "Accumulating evidence has shown that H19 gene polymorphisms are linked to cancer risk." (PMID 37480014, 2023). "H19 is found in some adult tissues such as skeletal muscle and the adrenal gland, and its dysregulation has been associated with many types of cancer although there are contrasting theories about its involvement in the progression of these cancers." (PMID 35880706, 2023). "Cancer-associated fibroblasts transfer exosomal lncRNA H19 to promote stemness and chemoresistance." (PMID 38054820, 2023). "Notably, H19 has been implicated in several mechanisms that increase the proliferation of cancer cells." (PMID 37821504, 2023). "Therefore, the aim of this meta-analysis was to accurately examine the correlation between H19 polymorphisms and cancer susceptibility." (PMID 37480014, 2023). "A hazardous effect on cancer development was observed in the H19 rs2839698 polymorphism under allele model (OR = 1.09, 95% CI = 1.01–1.18, p = 0.034); dominant model (OR = 1.11, 95% CI = 1.01–1.21, p = 0.029); and homozygous model (OR = 1.25, 95% CI = 1.07–1.46, p = 0.004) in all participates." (PMID 36588790, 2022). "Therefore, this updated systematic review and meta-analysis of all eligible studies aimed to explore a more precise understanding of the association between lncRNA H19 SNPs and cancer risk." (PMID 36588790, 2022). "Cancer-associated fibroblasts (CAFs) transfer exosomal lncRNA H19 into cancer cells." (PMID 35155247, 2022). "In this study, we collected all the relevant published data up to May 2022 to examine the association between lncRNA H19 rs2839698, rs217727, rs273597, rs2107425, rs3024270, rs3741216, and rs3741219 polymorphisms with cancer risk." (PMID 36588790, 2022). "In addition, we investigated the mechanism underlying the correlation of the H19 level in cancer tissue with poor prognosis in patients." (PMID 36090894, 2022). "In this study, we identified the H19 imprinting status in EBV-associated malignant tumor tissues." (PMID 35674441, 2022). "Among the LncRNA, the LncRNA H19 revealed certain associations to several types of cancers." (PMID 33799753, 2021). "H19 lncRNA is the primary transcript of H19 locus; after birth, the abnormal expression of lncRNA H19 was presented as a potential diagnostic biomarker in different cancers." (PMID 33541284, 2021). "Furthermore, H19 levels are negatively associated with miR-141 expression in GC cells, with H19 promoting malignancy while miR-141 plays an inhibitory role in human cancer cells." (PMID 34987543, 2021). "Although myriad researches upon the associations between LncRNA H19 polymorphic variants (rs2839698 G>A, rs217727 G>A, rs2107425 C>T, rs2735971 A>G and rs3024270 C>G) and the susceptibility to cancer have been conducted, these results remained contradictory and perplexing." (PMID 34310645, 2021). "LncRNAs HOTAIR, MALAT1, MEG3, and H19 are associated with a large number of cancer types." (PMID 34680193, 2021). "Moreover, LncRNA H19 showed a close association with high expressions of HCC cancer stem cell markers (such as CD90, CD44, and CD133) and the generation of GEM resistance in HepG2 cell line." (PMID 33402118, 2021).
cancer (continued). "The integration of the differentially expressed ncRNAs, with an exhaustive computational analysis of their experimentally supported targets, led us to dissect complex networks integrated by the cancer-related lncRNAs Malat1, Neat1, H19, Meg3, and their associated miRNA-target pairs." (PMID 34222014, 2021). "We also provided a summary of H19 genotype associations with cancer risks." (PMID 33800276, 2021). "Our study adds another piece of evidence that the H19 rs2839698 polymorphism may modulate the susceptibility to cancers." (PMID 33800276, 2021). "Taken together, our results and previous publications suggest that H19 may be implicated in the proliferation of OPC-like cancer cells, which are the cells of origin in DIPGs." (PMID 34502082, 2021). "Furthermore, we found that some lncRNAs including HOTAIR and H19 were associated with poor survival across multiple cancer types." (PMID 32231885, 2020). "In European Caucasians, H19 genetic polymorphisms (rs2107425 and rs2839698) might also be related to the susceptibility of cancer." (PMID 32337223, 2020). "Overexpression of H19 in many cancers is associated with acquired chemoresistance and cancer cell survival, involving various mechanisms of action such as oncogene expression, epigenetic gene silencing, enhanced cell proliferation, apoptosis inhibition, and metastasis." (PMID 33291403, 2020). "Furthermore, H19 SNPs have been associated with several types of cancer and with elevated serum levels of H19." (PMID 33329688, 2020). "Therefore, the present study was performed to summarize the overall diagnostic performance of lncRNA H19 in cancer detection and diagnosis." (PMID 31016202, 2019). "Therefore, in this study, we performed meta-analysis to comprehensively evaluate the association between H19 SNPs and susceptibility to cancer." (PMID 31752724, 2019). "Therefore, we performed this pooled analysis to evaluate the diagnostic value of H19 in cancer detection." (PMID 31016202, 2019). "Thus, we performed meta-analysis to explore the association between H19 polymorphisms and the risk of cancer." (PMID 31752724, 2019). "In addition, the introduction of the genome-wide association studies (GWAS) allowed for identification of an increased number of H19 SNPs that were associated with various types of cancer." (PMID 31752724, 2019). "In summary, all of the results indicated that H19 had a relatively moderate accuracy in distinguishing cancer patients from all individuals, suggesting that H19 could serve as a potential diagnostic biomarker for cancer detection and diagnosis." (PMID 31016202, 2019). "In addition, numerous studies have focused on the relation between H19 SNPs and cancer susceptibility." (PMID 31752724, 2019). "In addition, several recently published studies provide the basis for updating data sets and more accurately evaluating the relationship between H19 rs 217,727 and cancer risk." (PMID 31752724, 2019). "By now, some SNPs located on H19 gene were identified to be associated with cancer susceptibility." (PMID 31772668, 2019). "Such complexity may in part account for the discrepancy in the association between individual H19 SNP and distinct cancer types." (PMID 31277475, 2019). "Thus, this pooled analysis was conducted to summarize the overall diagnostic performance of lncRNA H19 in cancer detection and diagnosis and further explored its clinical value." (PMID 31016202, 2019). "H19 (Imprinted maternally expressed transcript) is known to be important for fertility and several processes associated with female disease risk, including cancer." (PMID 30567492, 2018). "All of these suggested that H19 genetic variants might have an important effect on cancer susceptibility." (PMID 30219045, 2018). "The pooled results showed that H19 rs2107425 had the borderline effect on cancer risk." (PMID 28159929, 2017).